KRAS (KRas proto-oncogene, GTPase)
Diseases named in the same sentence as KRAS in open-access papers (continued):
Sharing a sentence is not in itself a finding about the gene and the disease.
colorectal cancer (continued). "For example, National Comprehensive Cancer Network (NCCN) guidelines (version 2.2018) recommend KRAS, NRAS and BRAF mutation detection in metastatic colorectal carcinoma(CRC) for the well-established role in predicting therapeutic response." (PMID 35446881, 2022). "Moreover, this study detected DR5 expression in human PDAC and colorectal cancer tissues and found that high DR5 expression correlated with invasion of human PDAC into lymph vessels and with shortened metastasis-free survival of KRAS-mutated colorectal cancer patients." (PMID 33810241, 2021). "However, even with limited sample size, WGS was able to identify KRAS mutations in non-responders, which are frequently associated with treatment resistance in colorectal cancer, demonstrating the robustness of our approach." (PMID 34298611, 2021). "Recently, a phase I clinical study of lifirafenib (BGB-283), a RAF family kinase inhibitor, showed patients with KRAS-mutated endometrial cancer and NSCLC had a confirmed PR (n = 1 each), while no response was observed in patients with KRAS- or NRAS-mutated colorectal cancer (n = 20)." (PMID 34301278, 2021). "Thus, Yap1 gene amplification appears to occur in mice under KRAS ablation in a KRAS G12D-dependent mouse pancreatic tumor model, while a genome-scale cDNA screen identified activation of YAP1 as a factor for survival upon KRAS knockdown in KRAS G13D mutant colorectal cancer cell lines." (PMID 34685695, 2021). "Whereas, different from other studies that NTRK gene rearrangements are highly enriched in RAS wild-type colorectal carcinomas, there were only two classical fusion cases harboring KRAS (n = 1) and NRAS (n = 1) mutations; but no BRAF mutation cases were in our study." (PMID 33996597, 2021). "Herein, in KRAS mutant murine colorectal cancer CT26 syngeneic models, we investigate whether combination therapy with DC101 (a surrogate ramucirumab antibody, rat antimouse vascular endothelial growth factor receptor (VEGFR)-2 monoclonal antibody (mAb)) improves FTD/TPI efficacy." (PMID 33333866, 2020). "Further understanding of how KRAS activation drives Rab13-dependent EV secretion is required to determine the cellular contexts in which these EVs are regulated and released, and whether the affects we observe extend beyond colorectal cancer." (PMID 32978434, 2020). "Interestingly, however, the exon-4 KRAS mutation p.A146T detected in AMO1 was accompanied by a CN-gain (CN-status = 4) and a 2.3-fold higher mRNA-expression of KRAS reminiscent of the situation in colorectal cancer cell lines." (PMID 32079091, 2020). "In a previous study for quality assessment, we confirmed that KRAS and NRAS mutations may be present in the same population or different subpopulations of colorectal cancers according to an operating procedure proposed for validation of unexpected coexisting mutations." (PMID 32333643, 2020). "However, in spite of all this work, the overall metabolic dysregulation driven by different KRAS mutations in colorectal cancer is still not clear." (PMID 32300895, 2020). "Interestingly, in colorectal cancer, the most prevalent KRAS mutations, G12D and G12V, are weak drivers unlike BRAF600E which is a major driver." (PMID 32725342, 2020). "However, functional SMAD4 inactivation alone is not sufficient for tumour initiation, but it is thought to promote tumour progression in conjunction with additional alterations, e.g. activating KRAS (pancreatic duct adenocarcinoma) or inactivating APC alterations (colorectal cancer)." (PMID 32198650, 2020). "This might give an idea why KRAS mutations are frequent in colorectal cancer and may promote local invasiveness but probably do not determine the fate of metastasis." (PMID 33002027, 2020).
colorectal cancer (continued). "Although KRAS mutation analysis may provide additional useful information on risk stratification in colorectal cancer, the predictive value of KRAS mutation for non-response to chemotherapy is still questioning." (PMID 32070312, 2020). "MAP2K1 mutation has been identified among subsets of smoking-associated lung carcinomas (mutually exclusive from EGFR, BRAF, KRAS, and NRAS mutations), lung adenocarcinoma in situ and early invasive disease, and KRAS/NRAS/BRAF/PIK3CA wild-type (“quadruple-wild-type”) colorectal carcinomas." (PMID 32483240, 2020). "Moreover, it was demonstrated that PI3K activity is a main predictor of MEK-inhibitor resistance in KRAS-driven colorectal cancer and that the addition of a selective PI3K inhibitor could reverse acquired resistance to MEK-inhibition." (PMID 30691487, 2019). "Distribution of coexisting subclonal mutations in EGFR, KRAS, and NRAS in a subset of the patients with fusion-present colorectal cancer suggests that these fusions may arise as a novel mechanism of resistance to anti-EGFR therapies in patients with metastatic colorectal cancer." (PMID 33015522, 2019). "In colorectal cancer, it appears that loss of ARID1A in wild-type backgrounds may promote early tumorigenesis while loss of ARID1A in the background of mutations in APC or KRAS may inhibit tumor progression." (PMID 31217031, 2019). "However, colorectal cancers harboring constitutive activating mutations in KRAS, NRAS and BRAF genes are not responsive to anti-EGFR therapy." (PMID 31711486, 2019). "However, the oral MEK inhibitor RO4987655 (CH4987655) was not effective against KRAS-mutated colorectal cancer in a phase I study." (PMID 31769426, 2019). "Moreover, a KRAS synthetic lethal screening previously identified the related kinase DCLK2 as a hit in the colorectal DLD-1 cell line, suggesting DCLK1 as a potential target for combination therapy in the context of KRAS-mutated colorectal cancer." (PMID 31681616, 2019). "Nevertheless, secondary mutations in the extracellular domain of EGFR, mutations in KRAS, NRAS and C-Met, loss of PTEN and activating mutations in PIK3CA, and gain-of-activity in the IGFR pathway have been associated with acquired resistances of some cases of colorectal cancer." (PMID 31508364, 2019). "Glutathione was depleted by oxidative stress caused by increased DHA uptake via the GLUT1 glucose transporter and reduction of DHA back to vitamin C. Colorectal cancer cells with KRAS or BRAF mutation depend more on glycolysis than their nonmutated counterparts, not to mention normal cells." (PMID 31934267, 2019). "However, there are few natural products reported to act against KRAS-driven colorectal cancer." (PMID 30577618, 2018). "Among the most highly significant results, KRAS G12R appeared more strongly selected than other KRAS mutations, including KRAS G12C and G13D, in pancreatic cancer, as did BRAF V600E compared with other BRAF common mutations, including BRAF K601E, in thyroid, melanoma and colorectal cancer." (PMID 29748584, 2018). "In this study, we take advantage of chip-based and droplet digital PCR platforms and enumerate ctDNAs and miRNAs released from three human colorectal carcinoma (CRC) cell lines with different KRAS genotypes." (PMID 29941002, 2018). "Gene Expression Connectivity Mapping (GECM) provides an innovative approach in the discovery of new candidate compounds from previously FDA approved drugs, which may provide new insights into possible treatment strategies for KRAS mutant (KRAS-MT) colorectal cancer patients." (PMID 27965461, 2017). "Clinically, when treated with cetuximab, KRAS wild-type colorectal cancers experience on average a tumor decrease of only 41% after 24 weeks of treatment, leaving a significant tumor mass that could potentially develop additional genetic variant alleles associated with resistance." (PMID 28032592, 2017).
colorectal cancer (continued). "Currently, KRAS mutation status and microsatellite instability analysis are the only well-explained prognostic biomarkers as the negative predictors of the therapy efficiency in colorectal cancer." (PMID 28580315, 2017). "Although KRAS mutational status is an established negative predictor of response to anti-EGFR therapies in colorectal cancer, it is currently unknown if this status predicts response in patients with ABTC." (PMID 27853997, 2017). "Interestingly, high expression of LC3B was associated with decreased overall survival in the KRAS-mutated subgroup of colorectal cancers, but not in the KRAS-wildtype." (PMID 28696368, 2017). "HCT116 colorectal carcinoma cells harbor the mutated KRASG13D oncogene (common to 35-45% of CRC patients) and we sought to ascertain whether the cancer cell-induced alteration of CCD-18Co fibroblast gene expression was exclusively KRAS-dependent." (PMID 29245949, 2017). "However the multivariate analysis showed that age was not an independent predictor for KRAS mutation in colorectal cancer precursor lesions." (PMID 26910894, 2016). "In the 2012 Cancer Genome Atlas Network study, KRAS mutations presented in 43.0% of non-hypermutated colorectal cancers and 30.0% of hypermutated colorectal cancers while, BRAF mutations presented in 3.0% of non-hypermutated colorectal cancers and 47.0% of hypermutated colorectal cancers." (PMID 26910894, 2016). "Notably, oncogenic KRAS can regulate Death Receptors during metastasis in colorectal cancer cells." (PMID 27827395, 2016). "The predictive role of BRAF mutation in colorectal cancer is currently debated, but a recent meta-analysis indicated that BRAF mutation is a predictive biomarker of poor prognosis in mCRC patients treated by anti-EGFR monoclonal antibodies, especially in KRAS wild-type patients." (PMID 25983749, 2015). "This is a well-known KRAS activating mutation, whose role as a negative predictor for the efficacy of tyrosine kinase inhibitors has been clearly shown in non-small cell lung cancer and colorectal cancer." (PMID 25691052, 2015). "KRAS mutations can signal through the RAF-MEK-ERK MAPK pathway or the PI3K-AKT-mTOR pathway, suggesting that cytoplasmic localisation depending on KRAS mutant isoform may have predictive and prognostic utility in RAS mutant colorectal cancers." (PMID 26149458, 2015). "In colorectal cancer KRAS exons 12 and 13 mutations drive de novo or acquired resistance to anti-EGFR therapy and KRAS and/or BRAF status may change with time between primary and metastatic lesions in colorectal cancer in 17% of patients." (PMID 26474073, 2015). "Hence, the RALA pathway-responsive gene signature identified in the three colorectal cancer cell lines comprises 554 genes, irrespective of the mutational status of KRAS or BRAF." (PMID 26033452, 2015). "Further, the presence of mutations in RAS family oncogenes is associated with a lack of response to targeted therapy: lung and colorectal carcinomas characterized by KRAS mutations and KRAS and NRAS mutations, respectively are unresponsive to treatment with anti-EGFR agents." (PMID 26435479, 2015). "However, Loriot reviewed 6 clinical studies specifically looking at KRAS status in stage IV colorectal cancer and reported that KRAS mutations have no predictive value with conventional chemotherapy." (PMID 25491325, 2014). "We hypothesized that KRAS mutation status determined using PNA-PCR in tumor tissue and/or blood could be a powerful and easy-to-perform approach for planning treatment in patients with advanced colorectal cancer." (PMID 25491325, 2014).
colorectal cancer (continued). "In several studies, KRAS mutations in patients with colorectal cancer are associated with resistance to therapy with anti-EGFR antibodies and it is the only biomarker for predicting patient outcome when treated with targeted anti-HER therapies in colorectal cancer." (PMID 24609222, 2014). "Our recent study on colorectal cancers in detailed subsites (from cecum to rectum) has shown that tumor molecular features (including BRAF mutation, MSI and CIMP-high) change along the bowel subsites, and that cecal cancers are associated with KRAS codon 12 and 13 mutations." (PMID 24885062, 2014). "It was not our intention to explore all possible KRAS mutations that may be found in colorectal cancer, so we just targeted the mutations that are commonly involved in that disease." (PMID 25412182, 2014). "Such an imbalance might be considered a limitation of a small study such as COIN-B; however, the main reason for the imbalance between groups was discovered after the change in the population of interest from all patients with advanced colorectal cancer to those who had KRAS wild-type tumours." (PMID 24703531, 2014). "Since the characterization of the KRAS miRNA-related SNP known as KRAS-LCS6 (rs61764370), there have been a number of studies on the relationship of its genotype with risk 13–18 and prognosis 19–28 of several cancers, with many such studies directed toward colorectal cancer outcome 19–26." (PMID 24890702, 2014). "A meta-analysis demonstrated that the p.G12V mutation at codon 12 in the KRAS gene increases the risk of recurrence or mortality in patients with colorectal cancer, unlike other KRAS mutations that have only a moderate, non-significant effect on overall survival." (PMID 23761841, 2013). "KRAS mutations are used as negative predictors of antiEGFR therapies in colorectal cancer." (PMID 23506169, 2013). "Although several previous reports demonstrated the association between EREG (and/or AREG) expression and survival time in KRAS wild-type patients who had received Cetuximab, no previous paper reported the association in colorectal cancer patients who had never received anti-EGFR antibody." (PMID 22409860, 2012). "In the case of cetuximab treatment of colorectal cancer, which targets another receptor of the ERBB-family (the epidermal growth factor receptor) the expression of receptor ligands (i.e. amphiregulin and epiregulin), as well KRAS mutation, predict treatment response." (PMID 22014070, 2011). "Although KRAS mutations are consistently associated with reduced overall and progression-free survival (PFS) and increased treatment failure rates among patients with advanced colorectal cancer treated with anti-EGFR antibodies, no genetic and molecular markers for BV have been found." (PMID 21407216, 2011). "Using a similar approach, the use of two methylation panels as classifiers of colorectal cancer has been proposed: the first to identify highly methylated tumors (strongly correlated with BRAF) and a second to distinguish between intermediate (associated with KRAS) and low methylation groups." (PMID 21559209, 2011). "Therefore, lymph node metastases do not seem suitable for determination of the KRAS mutation status of colorectal carcinomas." (PMID 21364579, 2011). "The validation of KRAS mutations as a negative marker of response to anti-epidermal growth factor receptor (EGFR) antibodies has meant a seminal advance towards treatment individualisation of colorectal cancer (CRC) patients." (PMID 20234366, 2010). "Indeed, it was shown that KRAS activating mutations, occurring in different types of tumors, can be behind GLUT1 overexpression and also can be responsible for the increased glucose uptake in colorectal cancer cell lines." (PMID 20706540, 2010).
colorectal cancer (continued). "Recently a number of randomized trials have shown that treatment of patients with advanced colorectal cancer (CRC) do not benefit from therapies targeting the epidermal growth factor receptor (EGFR) when their tumors harbor mutations in the KRAS, BRAF and PIK3CA genes." (PMID 20098682, 2010). "Retrospective, subset analyses of tumor tissue samples from small clinical trials have demonstrated that tumor KRAS gene mutations are associated with lack of response to both of the EGFR-targeted monoclonal antibodies approved for use in colorectal cancer, cetuximab and panitumumab." (PMID 20877448, 2010). "Thus growth factor inhibitor treatment could be affected from the KRAS genotype in CC similarly to data in colorectal carcinoma." (PMID 20565817, 2010). "In contrast, mutations in PIK3CA are not mutually exclusive with KRAS in colorectal cancers." (PMID 19492075, 2009). "However, several groups have reported that KRAS mutations are significantly associated with lack of response to cetuximab or panitumumab in patients with advanced, chemotherapy-refractive colorectal cancer." (PMID 19545448, 2009). "Combining KRAS G12D and EGFR inhibition has demonstrated improved treatment efficacy, highlighting the potential of dual-targeting approaches in colorectal cancer therapy." (PMID 41604371, 2026). "Other emerging therapeutic approaches, such as targeting tumor metabolism processes, KRAS-targeted siRNA, anti-RAS vaccines, offer hope for inhibiting tumor growth and providing a potential treatment option for KRAS-mutant colorectal cancer." (PMID 40308511, 2025). "Next, we analyzed REGγ and KRAS-GTP protein expression across various human lung and colorectal cancer cell lines." (PMID 40091835, 2025). "In a multicenter Phase I/II trial, divarasib demonstrated a confirmed overall response rate (ORR) of 53% in KRAS G12C-mutant NSCLC and 29% in colorectal cancer (CRC), with median progression-free survival (PFS) of 13.1 months (NSCLC) and 5.6 months (CRC)." (PMID 41041285, 2025). "The RAS oncogene is represented by three primary isoforms—HRAS, KRAS, and NRAS—with KRAS being the most frequently identified in colorectal cancer patients." (PMID 40282985, 2025). "A potential interpretation is that colorectal cancers with suboptimal APC inactivation progress via alternative pathways, for example, increased KRAS signaling, in line with recent work suggesting pathway reciprocity between APC–MYC and KRAS pathways." (PMID 41091816, 2025). "While dual KRAS and epidermal growth factor receptor (EGFR) inhibition shows promise in treating KRAS-mutant colorectal cancer (CRC), resistance remains a major challenge." (PMID 41237766, 2025). "Similarly, the KRAS G12C inhibitors sotorasib and JDQ443 had also displayed inhibitory effects on HRAS G12C and NRAS C12C, with the combination therapy of sotorasib and EGFR antibody panitumumab being successfully used to treat a patient with colorectal cancer with NRAS p.G12C mutation." (PMID 40304209, 2025). "In KRAS-mutant colorectal cancer (CRC), de novo cholesterol biosynthesis induced GGPP biosynthesis-dependent proliferation of APC/KRAS-mutant CRCs via the GGPP-KRAS/MEK/ERK axis." (PMID 41184283, 2025). "Moreover, CDK4/6 inhibitors could downregulate pS6RP in KRAS-mutant colorectal cancers." (PMID 41428766, 2025). "Similar restoration of canonical KRAS signaling upon treatment with KRASG12C inhibitors by RTKs has been observed in other tumor types, such as colorectal cancer." (PMID 39253995, 2025).